REN (renin)
Diseases named in the same sentence as REN in open-access papers (continued):
Sharing a sentence is not in itself a finding about the gene and the disease.
Obesity (continued). "During hospitalization, patients with STEMI and obesity were more frequently prescribed beta-blockers and renin–angiotensin–aldosterone system inhibitors." (PMID 40564833, 2025). "The evidence indicates that the development of numerous MetS determinants, including low-grade inflammation, insulin resistance, renin-angiotensin-aldosterone system activation, and obesity, can be influenced by elevated fructose and sodium consumption." (PMID 40548446, 2025). "Several mechanisms have been proposed to drive glomerular hyperfiltration in obesity, including salt retention, activation of the renin–angiotensin–aldosterone and sympathetic nervous systems, and alterations in leptin signalling." (PMID 41282359, 2025). "Fourthly, obesity can trigger neuroendocrine alterations and activate the sympathetic nervous system, potentially resulting in excessive stimulation of the renin-angiotensin system." (PMID 40718102, 2025). "Studies suggest that chronic activation of the renin–angiotensin–aldosterone system (RAAS) in obesity exacerbates hypokalemia by increasing urinary potassium loss." (PMID 40136609, 2025). "Another interesting topic is the role of the renin–angiotensin and the kallikrein–kinin systems in obesity-related systemic complications." (PMID 40282897, 2025). "The higher drug CL in obese patients can also be explained by some physiological changes during obesity, such as increased blood flow, activation of the renin–angiotensin system, and glomerular hyperfiltration." (PMID 38895623, 2024). "Combined with EAT sympathetic hyperactivity and release of inflammatory adipokine leptin, this drives obesity‐mediated renin‐angiotensin‐aldosterone system activation and subsequent myocardial remodeling." (PMID 38156451, 2024). "Obesity over‐activates the classical arm of the renin‐angiotensin system (RAS), impairing skeletal muscle remodeling." (PMID 38684378, 2024). "In obesity, inflammatory cytokine increase and compression of the renal hilum by visceral adipose tissue activate the renin-angiotensin-aldosterone system." (PMID 39205686, 2024). "Overweight and obesity activate the renin-angiotensin-aldosterone system, while sympathetic activity is also increased." (PMID 39034410, 2024). "On the other hand, in people with obesity, the presence of increased insulin resistance is accompanied by the amplification of renin activity." (PMID 39062156, 2024). "Obesity increases glomerular filtration due to the activation of renal sympathetic activity, renin-angiotensin-aldosterone system, and insulin resistance." (PMID 39117944, 2024). "The risk factors of prediabetes, such as insulin resistance, adiposity, lipotoxicity and obesity, in conjunction with the alteration of the renin-angiotensin-aldosterone system (RAAS), have been positively correlated with the high morbidity and mortality rate." (PMID 38788045, 2024). "Third, an increase in visceral fat correlated with obesity affects the renin–angiotensin–aldosterone system (RAAS)." (PMID 39689101, 2024). "Abnormal adipokine production from adipose tissue, baroreceptor dysfunction, interaction with the renin–angiotensin–aldosterone system, and insulin resistance are among the causative pathways of SNS activation in obesity." (PMID 39457606, 2024). "In a study of HFpEF phenogroups, the phenogroup with a high incident of DM had the comorbidities of obesity and a high level of renin." (PMID 36836101, 2023). "Children with obesity had lower renin levels compared to the paediatric T1DM group although this difference was only significant in the male subjects." (PMID 36996194, 2023). "The level of Agt is positively associated with adipose tissue mass; and the upregulations of renin, Ace, and angiotensin II receptor type 1 (Agtr1) mRNA expression in the adipose tissue are observed in obesity." (PMID 37862361, 2023).
Obesity (continued). "Obesity, through the renin-angiotensin system (RAS), is involved in increasing sodium retention and increasing the release of adipokines, which are involved in the appearance of HBP." (PMID 37509651, 2023). "Patients with obesity tend to depict renin-angiotensin-aldosterone system (RAAS) overactivation, in result of the increased production of its substrates by adipocytes, as well as from renal sympathetic nervous system overactivation." (PMID 37816974, 2023). "In obesity, there is an activation of the sympathetic nervous system, renin-angiotensin-aldosterone system all contributing to the high BP in overweight and obese participants." (PMID 37484578, 2023). "In this study, we investigated the relation between urinary EGF, serum renin and blood pressure in children with obesity or T1DM." (PMID 36996194, 2023). "Partial correlations, controlling for age and height z-score, between renin, uEGF/uCreatinine eGFR and blood pressure parameters in boys and girls with obesity or T1DM." (PMID 36996194, 2023). "Elevated levels of Agt were observed in adipose tissue of rats suffering from primary hypertension and obesity, and the levels and capacities of Agt, plasma renin, and angiotensin-converting enzyme in the adipose tissue were directly correlated with obesity." (PMID 38155947, 2023). "In fact obesity via enhancing the activity of renin–angiotensin–aldosterone system and the sympathetic nervous system." (PMID 36907869, 2023). "Both in boys with T1DM and boys with obesity, the serum renin levels are higher when compared to girls." (PMID 36996194, 2023). "Obesity activates the renin-angiotensin system and the sympathetic nervous system, which leads to increased sodium reabsorption and arterial blood pressure." (PMID 35287586, 2022). "Obesity is associated with RAAS overactivation, as demonstrated by increased adipose tissue MR expression and elevated plasma levels of aldosterone, renin, angiotensinogen, angiotensin-converting enzyme (ACE), and AT II." (PMID 35043013, 2022). "Obesity can activate the renin-angiotensin-aldosterone system, leading to the retention of water and sodium, which increases the cardiac afterload and results in ventricular remodeling." (PMID 35620321, 2022). "Obesity is further characterized by a hyperdynamic circulatory status with higher blood volume, increased heart rate, and an activated angiotensin-renin axis." (PMID 36684585, 2022). "The enhanced activation of the renin–angiotensin–aldosterone system in obesity further contributes to vascular insulin resistance and endothelial dysfunction." (PMID 35055038, 2022). "Obesity also activates the renin–angiotensin and sympathetic nervous systems, which are associated with GHF, IR, and NAFLD." (PMID 35887639, 2022). "Overweight and obesity increase renal sodium reabsorption and activate the renin-angiotensin and sympathetic nervous systems which elevate BP." (PMID 36235676, 2022). "In humans and animal models of obesity, activation of the renin–angiotensin–aldosterone system (RAAS) has been observed to be associated with enhanced oxidative stress and inflammation in the vascular tissue." (PMID 34436493, 2021). "UNx and UNx-Renin mice demonstrated a significantly higher degree of obesity and hyperglycaemia compared to lean db/m controls (both P<0.001)." (PMID 34494644, 2021). "The overproduction of aldosterone in obesity occurs through 2 pathways: 1- renin-angiotensin system activation stimulates aldosterone secretion from the adrenal cortex and the adipocytes." (PMID 35242044, 2021). "Several clinical studies suggest an important role of the renin-angiotensin-aldosterone system in the pathophysiology of obesity and the MetS." (PMID 33809055, 2021). "One important mechanism by which salt sensitivity was increased in obesity was an activation of the intrarenal renin-angiotensin-aldosterone system (RAAS)." (PMID 34568382, 2021).
Obesity (continued). "The renin-angiotensin system (RAS) is present in adipose tissue, and evidence suggests that it is involved in both diet-induced obesity and the inflammation associated with obesity." (PMID 34149621, 2021). "The mechanisms through which obesity causes HTN are complex, including sympathetic nervous system over‐activation, stimulation of the renin‐angiotensin‐aldosterone system, alterations in adipose‐derived cytokines, structural functional renal changes, and IR." (PMID 34269508, 2021). "In contrast, the role of gender seems to be related to renin activity; female mice overexpressing human renin are protected from HFD-induced obesity." (PMID 34107965, 2021). "No statistical differences were found in measurements of renal function, vitamin D levels, or the hormones renin, aldosterone, and cortisol across classes of obesity." (PMID 33748038, 2021). "Increased inflammation, oxidative stress, increased renin-angiotensin-aldosterone system, and insulin resistance are known as mechanisms of renal failure in obesity." (PMID 34535101, 2021). "Plasma renin activity displayed significant increase in obesity and local perivascular adipose tissue angiotensin II is also increased." (PMID 34960033, 2021). "Dysregulation of the renin-angiotensin system (RAS) has a critical role in the pathogenesis of kidney injury in obesity." (PMID 34568382, 2021). "Obesity promotes increased plasma renin activity plasma angiotensinogen and angiotensin-converting enzyme (ACE) activity, promoting enhanced plasma levels of Ang II in obese patients." (PMID 33800427, 2021). "WAT and BAT express all the components of the renin-angiotensin system (RAS), and the renin-angiotensin system is involved in obesity and insulin resistance." (PMID 33670130, 2021). "Kalupahana NS, Moustaid-Moussa W. The renin-angiotensin system: a link between obesity, inflammation and insulin resistance." (PMID 32785498, 2020). "Other obesity-related pathways were enriched, including insulin resistance (six DEGs), renin secretion (five DEGs), aldosterone synthesis and secretion (six DEGs), and melanogenesis (five DEGs)." (PMID 32899471, 2020). "Overactivation of the renin–angiotensin system (RAS) during obesity disrupts adipocyte metabolic homeostasis and induces endoplasmic reticulum (ER) stress and inflammation; however, underlying mechanisms are not well known." (PMID 32466437, 2020). "Because obesity increases sodium retention, which results in salt-sensitive hypertension, it induces higher levels of aldosterone and renin by invoking the aldosterone-renin–angiotensin system." (PMID 32899471, 2020). "The renin-angiotensin system (RAS) hyperactivity is one of the central mechanisms of cardiovascular diseases related to obesity." (PMID 33519529, 2020). "According to some authors, the renin-angiotensin system (RAS) constitutes a possible link between obesity and CVDs." (PMID 31365628, 2019). "In contrast to male mice, female mice overexpressing human renin are protected from HFD-induced obesity." (PMID 31262355, 2019). "Obesity has several effects on renal physiology, including insulin resistance, inflammation, oxidative stress, renin-angiotensin-aldosterone, and hyperlipidemia." (PMID 31498850, 2019). "While still an active area of investigation, emerging evidence suggests that sex differences in obesity are, at least in part, attributed to hormonal mediators such as the renin-angiotensin system (RAS)." (PMID 31262355, 2019). "Contributing factors to the pathophysiology of CKD in obesity include the activation of the renin-angiotensin-aldosterone system, increased sympathetic nervous activity, insulin resistance, and oxidative stress." (PMID 34466454, 2019). "Obesity increases renal sodium reabsorption and impairs PN by activation of the renin–angiotensin and sympathetic nervous systems and by altered intrarenal physical forces." (PMID 31537914, 2019).
Obesity (continued). "Individuals with obesity are often reported to have increased plasma renin and angiotensin converting enzyme (ACE) activities, plasma angiotensinogen (AGT), angiotensin II (ANG II), or aldosterone levels." (PMID 29540174, 2018). "Stimulation of the renin-angiotensin system (RAS) has been reported as one of the essential mechanisms in obesity-related hypertension." (PMID 29636702, 2018). "The factors generally considered responsible for obesity-related blood pressure elevation include an enhanced sympathetic tone, activation of the renin-angiotensin system (RAS), hyperinsulinemia, structural changes in the kidney, and elaboration of adipokines." (PMID 29099041, 2017). "We have previously reviewed the role of systemic and adipose tissue renin-angiotensin systems in obesity-related HT." (PMID 28637427, 2017). "Obesity leads to the up-regulation of renin–angiotensin–aldosterone axis and sodium and fluid retention." (PMID 29070064, 2017). "Genetic depletion of renin, the rate-determining enzyme for the generation of angiotensin, has been shown to result in resistance to diet-induced obesity and a reduction in fatty liver in mice." (PMID 26732252, 2016). "Obesity can lead to increased renal sodium reabsorption and renal injury through the activation of the renin-angiotensin system and increased sympathetic tone." (PMID 26893938, 2015). "These mediators interact with the sympathetic nervous system, the renin-angiotensin-aldosterone system and individual organs -such as the pancreas and liver- to effect the alterations in physiology that accompany obesity." (PMID 26141622, 2015). "This is because obesity increases insulin release which then thickens blood vessels in addition to release of renin and aldosterone." (PMID 25135002, 2014). "Activation of the renin-angiotensin–aldosterone system is involved in diet-induced obesity, since hypertrophied adipocytes can serve as a source of angiotensin II." (PMID 24490784, 2014). "In fact, enhanced activity of the RAS, represented by increased circulating angiotensinogen, renin, aldosterone, and angiotensin-converting enzyme activity has been reported in obesity." (PMID 25170617, 2014). "Since PPARgamma is activated during obesity and since it stimulates the renin gene expression, the intriguing possibility exists that the activated PPARgamma increases the renin production in MetS patients, thus acting prohypertensively." (PMID 24288524, 2013). "Given that angiotensin II negatively influences systemic glucose metabolism and that augmented activity of the renin-angiotensin system is found in obesity, attention has lately focused on the effect of this hormone in adipose tissue." (PMID 24098385, 2013). "In previous research, renin knock-out mice were found to exhibit resistance to diet-induced obesity with the beneficial metabolic changes in these mice being reversed by angiotensin II administration." (PMID 24204981, 2013). "We and others have recently documented the contribution of adipose tissue renin-angiotensin system to the pathogenesis of obesity, inflammation, and insulin resistance." (PMID 23483012, 2013). "Enhanced AAR activates sympathetic nervous system and increases circulating renin, angiotensin II (Ang II), and norepinephrine (NE) levels in the obesity hypertensive rats." (PMID 24244673, 2013). "Increasing evidence suggests that the renin-angiotensin system (RAS) contributes to the etiology of obesity." (PMID 22880127, 2012). "Various explanations are plausible, such as coexistence of obesity, lipotoxicity, activation of renin-angiotensin system and cardiac insulin resistance." (PMID 22347376, 2012). "Nevertheless, differently from other obesity models, the obese Zucker rats have low plasma levels of renin." (PMID 23077501, 2012). "The relation between ACE and obesity has been suggested to lie in the local expression of the renin-angiotensin system and the possible trophic role of angiotensin II in the development of adipose tissue." (PMID 21340022, 2011).
Obesity (continued). "In addition HFD resulted in hyperinsulinemia, activation of the renin-angiotensin system, glomerular hyperfiltration and structural changes in the kidney that may be the precursors of more severe glomerular injury associated with prolonged obesity." (PMID 19835614, 2009). "Obesity potentiates the sympathetic activation seen in heart failure leading to renin-angiotensin-aldosterone axis activation, resulting in further salt and fluid accumulation." (PMID 19133159, 2009). "Moreover, obesity can cause damage in the glomerular hemodynamics, leading to an overactivation of the renin-angiotensin-aldosterone system and finally obesity-induced nephropathy." (PMID 39836643, 2025). "Obesity-related HTN is thought to be associated with activation of the sympathetic nervous system, intra-abdominal and intravascular fat, sodium retention, increased renal reabsorption, and the renin–angiotensin system." (PMID 39857161, 2025). "The obesity-related activation of the renin–angiotensin system may also play a role in cardiac remodelling." (PMID 40422864, 2025). "Pharmacotherapies targeting RAAS, including ACE inhibitors, angiotensin receptor blockers, mineralocorticoid receptor antagonists (MRAs) or renin inhibitors, may decrease high BP among patients with obesity." (PMID 40761303, 2025). "Furthermore, renin–angiotensin–aldosterone system (RAAS) modulators play a crucial role in improving sodium and potassium balance while reducing the risk of obesity-related hypertension and kidney dysfunction." (PMID 40136609, 2025). "Further, activation of the renin–angiotensin–aldosterone system in obesity, which plays an important role in the hemostasis of the cardiovascular system, stimulates inflammation and structural remodeling under pathophysiological conditions, thus inducing cardiac and vascular injury." (PMID 40732953, 2025). "In obesity, the increase in circulating FFAs that occurs with increased lipolysis contributes to the development of insulin resistance, glucose intolerance, and hypertension through combined effects on skeletal muscle and the renin–angiotensin system." (PMID 40422864, 2025). "For instance, addressing insulin resistance and obesity may interact to activate the renin/angiotensin/aldosterone system and the sympathetic nervous system, resulting in reduced vascular tone and stiffness." (PMID 40364032, 2025). "There are several hypothesized mechanisms in the obesity paradox, including lower increases of plasma renin and angiotensin as a response to stress giving a better outcome and providing greater metabolic reserves to counteract increased catabolic stress." (PMID 40395862, 2025). "Obesity is associated with a mild-to-moderate increase in both systemic and local adipose RAAS activity despite sodium retention and elevated BP, factors that should physiologically inhibit renin secretion, AngII formation and aldosterone secretion." (PMID 38186879, 2024). "In addition, obesity can increase the blood pressure through the activation of the Renin-Angiotensin-Aldosterone System by hormones and cytokines which are produced by the adipose tissue." (PMID 38541014, 2024). "In obesity patients, pro-inflammatory and vasoactive adipokines such as angiotensinogen, angiotensin II, aldosterone, and resisting, along with increased plasma renin activity and cytokines are hypersecreted." (PMID 38978621, 2024). "Mechanistic insights into how obesity promotes renal dysfunction through lipid metabolism, inflammation, and altered renal hemodynamics are elucidated, underscoring the role of adipokines and the renin–angiotensin–aldosterone system." (PMID 39459455, 2024). "Moreover, the overproduction of angiotensin II by hypertrophic adipocytes leads to overactivation of the renin–angiotensin–aldosterone system in obesity, further exacerbating arterial vasoconstriction." (PMID 39728435, 2024).